FLT3 (fms related receptor tyrosine kinase 3)
Diseases named in the same sentence as FLT3 in open-access papers (continued):
Sharing a sentence is not in itself a finding about the gene and the disease.
leukemia (continued). "This pattern of FLT3 expression in leukemia is in contrast to KIT and FMS expression, which are typically restricted to myeloid leukemia." (PMID 25295230, 2014). "Bone marrow from Flt3 null mice transduced with MLL-ENL or MLL-CBP was transplanted into host mice and Flt3−/− leukemias were compared to their Flt3 wild type counterparts." (PMID 23977266, 2013). "Using Flt3 knock out mice, we previously found that leukemias induced by the retroviral transduction of Hoxa9 and Meis1, which recapitulate many features of MLL-rearranged myeloid leukemias, are Flt3 independent." (PMID 23977266, 2013). "Recently, there has been an increased interest in utilizing small molecule kinase inhibitors to target aberrant TK activity of FLT3 mutants that contribute to leukemia growth and poor outcome in AML patients." (PMID 23497456, 2013). "We therefore utilized FLT3-mutated leukemia cell lines of MV4;11 and Ba/F3-ITD to confirm the cell protective effects of TGF-β on FLT3-ITD positive cells under BM microenvironment." (PMID 23826077, 2013). "Two studies have shown that cultured leukemia cells from pediatric MLL-rearranged ALLs are more sensitive to the cytotoxicity of FLT3 inhibitors, PKC412 or CEP-701, than ALL cells with germline MLL expressing lower levels of FLT3." (PMID 23977266, 2013). "As was reported for human MLL-rearranged blasts, leukemia cells expressing higher levels of Flt3 are more sensitive to the cytotoxicity of PKC412." (PMID 23977266, 2013). "As previously reported for human MLL-rearranged leukemias, murine MLL-ENL leukemia cells with higher Flt3 levels were more sensitive to the cytotoxicity of PKC412." (PMID 23977266, 2013). "Quizartinib potently inhibits cellular proliferation and induces apoptosis in leukemia cell lines that are dependent on FLT3, KIT or PDGFRA activity." (PMID 23497317, 2013). "In agreement with the heterogeneous levels of Flt3 protein seen by immunobloting, the percentage of Flt3-expressing cells measured by flow cytometry was variable among the leukemia samples." (PMID 23977266, 2013). "This study investigates the regulation and function of PRL-3 in leukaemia cell lines and AML patients associated with FLT3-ITD mutations." (PMID 23929599, 2013). "A striking feature of leukemias with the DEK-NUP214 fusion gene is the concomitant internal tandem duplication (ITD) in the tyrosine kinase FLT3." (PMID 24073922, 2013). "In general, the reported IC50s in our study for native leukemia cells lie in contrast to a previous report by Zarrinkar and colleagues, which have suggested IC50s for FLT3 ITD-positive native blasts in the lower nanomolar ranges." (PMID 23497317, 2013). "The upregulation of FLT3 and autocrine or paracrine activation by its ligand can lead to excessive FLT3 signaling in leukemia." (PMID 23977266, 2013). "Our objective was to determine the role of Flt3 in the pathogenesis of MLL-rearranged leukemias and to use a murine leukemia model to study the sensitivity of blasts to FLT3 inhibition ex vivo." (PMID 23977266, 2013). "Emerging small molecule inhibitor compounds have been shown to interfere with the aberrant FLT3 TK activity and lead to arrest of leukemia growth." (PMID 23497456, 2013). "We sought to determine the contribution of Flt3 in the pathogenesis of MLL-rearranged leukemias using a myeloid leukemia mouse model." (PMID 23977266, 2013). "Potent inhibition of amplified FLT3 wildtype gene via quizartinib was recently shown in an in vitro leukemia cell model using the SEM-K2 ALL cell line by Gunawardane and colleagues." (PMID 23497317, 2013). "To examine if Flt3 was important for leukemia transplantability, we studied the ability of Flt3+/+ and Flt3−/−MLL-ENL leukemias to engraft into secondary recipients." (PMID 23977266, 2013). "The presence of Flt3 did have a notable effect on leukocytosis with a considerable reduction in circulating blasts in Flt3−/− MLL-ENL leukemias compared to their Flt3+/+ counterparts." (PMID 23977266, 2013).
leukemia (continued). "Murine models to determine the role of Flt3 in the pathogenesis of MLL-rearranged leukemias have shown contradictory results." (PMID 23977266, 2013). "Excessive expression of FLT3 in MLL-rearranged leukemias results from direct transcriptional activation by HOXA9 and MEIS1 and post-transcriptional regulation by miR-150, a microRNA whose level is repressed by MLL fusion genes." (PMID 23977266, 2013). "The ultimate evaluation of the therapeutic benefit of FLT3 inhibitors against MLL-rearranged leukemias awaits results of clinical trials in patients." (PMID 23977266, 2013). "First, the analysis of primary FLT3-ITD+ AMLs showed that the CD34+/CD38− fraction of these leukemias enriched in cells with the property of LSCs, containing the FLT3-ITD mutation." (PMID 23936658, 2013). "To determine the anti-leukemic effect of FLT3 inhibition we studied the sensitivity of MLL-ENL leukemia cells to the FLT3 inhibitor PKC412 ex vivo." (PMID 23977266, 2013). "Most importantly, we showed a remarkable in vivo activity of silvestrol in a FLT3-ITD leukemia engraftment model." (PMID 23497456, 2013). "Gain-of-function mutations of the tyrosine kinase (TK) receptor encoding gene FLT3 occur in approximately 30% of AML patients, and result in constitutive TK activity and, in turn, increasing growth and survival of leukemia blasts." (PMID 23497456, 2013). "This is supported by studies of primary human MLL-rearranged leukemia cells in which PKC412 doses required for repression of cell growth were considerably higher than those sufficient to fully inhibit FLT3 phosphorylation." (PMID 23977266, 2013). "Various FLT3 or KIT leukemia cell lines and native blasts were used to determine the antiproliferative and proapoptotic efficacy of quizartinib." (PMID 23497317, 2013). "In contrast, a recent study showed that shRNA-mediated knock-down of Flt3 increases the latency of MLL-AF9 induced leukemias in transplanted mice, supporting the notion that Flt3 is a worthy drug target." (PMID 23977266, 2013). "The constitutive activation of STAT5 has a pivotal role in FLT3-ITD leukaemia cell expansion and survival." (PMID 22187040, 2012). "Despite the known role of DUSP6 as negative regulator of ERK1/2 activation, which was also observed in FLT3 ITD-expressing leukemia cells, DUSP6 was identified as a positive component in the FLT3 ITD-driven proliferation." (PMID 22784513, 2012). "Ten patients (24%) proved refractory, but only 5/10 belonged to a high-risk category (4 FLT3 ITD+, 1 secondary leukemia)." (PMID 23205260, 2012). "To develop a better understanding of FLT3 signaling as well as its downstream effectors, we performed detailed phosphoproteomic analysis of FLT3 signaling in human leukemia cells." (PMID 21552520, 2011). "This study showed that oncogenic FLT3 regulates proteins involving diverse cellular processes and affects multiple signaling pathways in human leukemia that we previously appreciated, such as Fc epsilon RI-mediated signaling, BCR, and CD40 signaling pathways." (PMID 21552520, 2011). "In a previous survey of canine leukemias, a heterozygous FLT3 ITD was found in 3/36 (~8.3%) dogs diagnosed with ALL." (PMID 21272320, 2011). "Three resistant cell lines (designated as MV4–11-R1, -R2, -R3) were developed by over three-month co-culture of the human leukemia cell line, MV4–11 (AML, both alleles FLT3-ITD) with increasing concentrations of ABT-869." (PMID 19642998, 2009). "For leukemia cell lines with FLT3-ITD such as MV4–11 and MOLM-14, ABT-869 potently inhibits their proliferation at IC50 less than 10 nM." (PMID 19642998, 2009). "FLT3/ITD+ is found in 20% to 30% of de novo AML patients and is the most mutated gene in leukemia, with a significant clinical impact on patients." (PMID 19466291, 2009). "In clinical trials, FLT3 inhibitors reduced FLT3 phosphorylation, and lowered leukemia blast counts in patients with advanced therapy-refractive AML." (PMID 19330068, 2008).
leukemia (continued). "FLT3 inhibition induces terminal myeloid differentiation, which may lead to the appearance of persistent leukemia." (PMID 41521262, 2026). "FLT3 mutations lead to abnormal activation of the FLT3 receptor, which continuously activates downstream signaling pathways such as Ras/MAPK/, STAT5, PI3K/Akt/mTOR, inhibits cell apoptosis, and promotes the proliferation and survival of leukemia cells." (PMID 40722724, 2025). "As such, inhibition of lipid biosynthesis may be a metabolic vulnerability in FLT3/ITD leukemia cells and could be exploited for treatment of this subtype of leukemia." (PMID 40263296, 2025). "Compared to current targeted therapies, which often address single genetic mutations (e.g., FLT3, IDH1/2), the multi-targeted nature of YWLS-derived compounds offers broader anti-leukemia effects and may overcome the limitation of clonal heterogeneity." (PMID 40520175, 2025). "However, at the second relapse, an additional mutation was detected in FLT3-TKD, which, along with EZH2, propagated overt leukemia." (PMID 40362463, 2025). "Nevertheless, given the poor prognosis and high relapse rate, patients with NUP98r leukemia may benefit from FLT3 inhibitors, BCL2 inhibitors, and CDK4/6 inhibitors, as well as hematopoietic stem cell transplantation." (PMID 40264981, 2025). "Our results indicated that FLT3/ITD may play an important role in regulating SREBP expression at the protein level in leukemia cells." (PMID 40263296, 2025). "To understand whether OSM is functionally relevant for the disease progression of leukemia, we used Osm-deficient mice or WT mice as BM donors in models of FLT3-ITD- and BCR::ABL1-positive leukemia." (PMID 41372120, 2025). "Thus, we sought to discover the pathways responsible for the ERK reactivation seen in FLT3 inhibition of FLT3/ITD leukemia." (PMID 39395205, 2025). "Innovative approaches, such as the development of allosteric inhibitors or dual inhibitors targeting multiple pathways (e.g., JAK2 and FLT3), may offer more effective treatments for leukemia subtypes that are refractory to current therapies." (PMID 40486651, 2025). "Indeed, preclinical studies showed that ATRA synergizes with FLT3 TKIs to eliminate FLT3-mutant leukemia stem cells." (PMID 41228209, 2025). "By combining JAK2 inhibitors with other targeted therapies, such as inhibitors of BCL-2 (to promote apoptosis) or FLT3 inhibitors (to block additional tyrosine kinase signaling), it is possible to simultaneously target multiple signaling pathways that drive leukemia." (PMID 40486651, 2025). "Furthermore, the previous study has identified that the upregulation of class I HDAC member HDAC8 following FLT3 inhibition contributes to resistance and promotes leukemia maintenance." (PMID 39955584, 2025). "Conversely, we found that FLT3-ITD and IDH1 mutations were more frequent at R/R, supporting the idea that these leukemias could be more resistant (although the prognostic impact of IDH1 remains controversial)." (PMID 40075701, 2025). "CHR rate: 83.3% of patients (20/24) achieved complete remission (true or with insufficient hematological recovery).Reduction in ITD Allelic Burden: Significant reduction of FLT3-ITD allelic burden in patients.OS:Median Leukemia-Free Survival: 12 weeks.Median Overall Survival: 33 weeks." (PMID 39949739, 2025). "A number of Flt3 inhibitors have been developed for leukemia treatment." (PMID 40076904, 2025). "Identification of additional FLT3/ITD-specific metabolic vulnerabilities may offer new therapeutic opportunities for this refractory subtype of leukemia." (PMID 40263296, 2025). "We next sought to determine whether fatostatin or orlistat could enhance the anti-leukemia activity of FLT3 tyrosine kinase inhibitor in vivo." (PMID 40263296, 2025).
leukemia (continued). "Pharmacological inhibition of SREBP1 or FASN sensitized FLT3/ITD leukemia cells to quizartinib." (PMID 40263296, 2025). "Second, relevant genetic subgroups were excluded (i.e. mutant-NPM1 and FLT3 ITD leukemias), which may specifically benefit from such an approach as suggested by our multivariate analysis." (PMID 38195541, 2024). "In addition, it is worth mentioning that mutated FLT3 (ITD) and mutated NPM1 are also leukemia-specific target antigens in AML, which are associated with CD8+ T-cell responses." (PMID 39582863, 2024). "Interestingly, we found that ningetinib outperformed the other tested drugs in the in vivo experiments in mouse models of leukemia driven by either FLT3-ITD or FLT3-ITD-F691L." (PMID 38978049, 2024). "It was shown in a non-leukemia model that the FLT3-ITD mutation produces functional DCs without pathogenic side effects but does result in increased DC abundance and moderate effects on CD4+ T cell phenotype." (PMID 38495876, 2024). "Despite allogeneic hematopoietic stem cell transplant (allo-HCT) and the development of novel FLT3 inhibitors in both induction (midostaurin) and in the relapsed/refractory setting (gilteritinib), FLT3-ITD mutated leukemia (FLT3-ITD+ AML) still represents a challenge for modern hematology." (PMID 38978738, 2024). "Furthermore, HSC-prog cells showed more interactions with other cells through known ligand–receptor pairs, such as leukaemia-associated ligands CXCL2, CXCL3, and FLT3, signalling to the receptors CXCR1 and CXCR2 expressed by CD14-mono and NK cells." (PMID 37615858, 2024). "Indeed, the development of FLT3 inhibitors represents a significant advancement in leukemia therapy, offering potential ways for improved treatment outcomes." (PMID 38612443, 2024). "Thus, the role of FLT3 and the FLT3 ligand in immunity and leukemia is complex, with features suggestive of an anti-tumor response but also leukemic stimulation." (PMID 39200232, 2024). "Furthermore, mutated FLT3 (ITD) and NPM1 are leukemia-specific target antigens in AML, associated with CD8+ T-cell responses." (PMID 39582863, 2024). "This study may provide a useful strategy to design nanomedicines capable of augmenting the therapeutic efficacy of FLT3 inhibitors for effective leukemia therapy." (PMID 38257023, 2024). "This is consistent with our evidence that HOXA9 could restore the FLT3 expression in RBM5 null leukemia cells." (PMID 38216972, 2024). "Synergistic suppression of proliferation was triggered by this particular drug combination and increased apoptosis in KMT2A‐r leukemias with an FLT3 mutation as opposed to single‐drug therapy." (PMID 39428967, 2024). "In various human leukemias (such as AML and infant/childhood ALL), expression of mutated FLT3, harboring internal tandem duplications of the juxtamembrane regions (FLT3/ITD), constitutively activates cell proliferation and survival pathways and is associated with poor prognosis." (PMID 39125761, 2024). "However, quizartinib also possesses activity against wild-type Flt3, as it is the case for many other Flt3-specific and multi-targeting TKIs that are in use for leukemia and solid tumor therapy." (PMID 37945814, 2024). "Thus, the autophagosome formation inhibition-mediated activation of AIM2 inflammasome can also synergize with a molecular-targeted drug, FLT3 inhibitor, to induce irreversible differentiation in leukemia cells with FLT3-ITD even in the presence of FGF2." (PMID 38466568, 2024). "Together, SUCLG1 and POLRMT are essential for mutant FLT3-driven leukemia." (PMID 38649537, 2024). "In addition, considering the propensity of leukemia to develop resistance to FLT3 inhibitors, we need to gain a deeper understanding of the mechanism by which FLT3 signals in AML cells." (PMID 38915288, 2024). "The data above demonstrate that MA49 has superior activity against leukemia cells with FLT3-ITD." (PMID 39300221, 2024). "Next, we tested the regulation of SUCLG1 by FLT3 in human leukemia cells." (PMID 38649537, 2024).